GFAP (glial fibrillary acidic protein)
Diseases named in the same sentence as GFAP in open-access papers (continued):
Sharing a sentence is not in itself a finding about the gene and the disease.
tumor (continued). "In addition, areas of tumor cell foci showed extensive Ki-67 expression, strong CD31 staining demonstrated that the tumor was highly angiogenic, and displayed GBM tumor stem cell positive markers such as SOX2 and GFAP." (PMID 36506083, 2022). "Tumor cells were negative for glial fibrillary acidic protein (GFAP, marker of astrocytes) and ionized calcium-binding adapter molecule (Iba1, marker of microglial cells), in the presence of inner positive controls." (PMID 36288154, 2022). "We reported a 14-year-old patient with autoantibodies against both DPPX and GFAP; however, no tumor was detected within 1 year of follow-up." (PMID 35382765, 2022). "While some oligosarcomas retained positivity in many tumor cells, others were mostly negative and yet others displayed a patchy GFAP expression pattern." (PMID 34967922, 2022). "We have shown that parameters which are dependent on the patient rather than tumour characteristics, such as the patient's healthy baseline GFAP serum levels and the GFAP decay rate, also impact detection." (PMID 35919979, 2022). "GFAP is produced as a consequence of necrotic growth not tumour growth and although the two are related it is possible to have a tumour which grows faster without having faster necrotic growth." (PMID 35919979, 2022). "Immunostaining for GFAP and OLIG2 revealed entrapped reactive glial cells among all tumor samples." (PMID 36423085, 2022). "GFAP expression was only categorized as positive if expression was detected in all analyzed slides; if GFAP expression was lost in a single fraction of tumor cells the tumor was classified to be overall negative." (PMID 35073955, 2022). "Tumor cells were negative for GFAP, synaptophysin, keratins (Cam5.2, pancytokeratin), inhibin, carbonic anhydrase, PAX8, and D2-40." (PMID 34925233, 2021). "However, GFAP stained histologies reveals small GBM traces in all these samples, meaning that these tumor infiltrations are below the 3.253 μm3 voxel size detectability limit." (PMID 34638437, 2021). "In addition, the overexpression of glial fibrillary acidic protein (GFAP), a component of intermediate filaments and hence a part of the cytoskeleton, is believed to decrease cell proliferation and tumor growth." (PMID 33690729, 2021). "Fluorescence was also detected in glial cells (GFAP+) without discrimination between the U87 tumor cells and the host glial cells." (PMID 34069377, 2021). "First, it does not depend on the expression of tumor cell surface markers, such as EpCAM and GFAP; thus, the CTC tracer is independent of the expression levels of cell surface markers and specific molecular types." (PMID 34763698, 2021). "A specimen obtained from the region of abnormal FLAIR signal adjacent to the tumor revealed scattered atypical cells with reactive astrocytosis as confirmed by GFAP immunostain, but no microvascular proliferation (MIB1 < 1%) or necrosis." (PMID 34355174, 2021). "Most of the astrocytes (GFAP+) and neurons (Neu N+) were found localized in the hippocampus (H) of the brain tissue, but not found at the tumor site (T)." (PMID 34439274, 2021). "In the tumor group of mice, GFAP levels increased significantly from day 10 to 21, but no obvious change was detected in the sham group of mice." (PMID 32796132, 2020). "The tumor was negative for S100 protein, cytokeratin (CK), glial fibrillary acidic protein (GFAP), CK7, SOX10, CD31, CD34, desmin, MyoD1, myogenin, smooth muscle actin (SMA), CD117, β-catenin and MUC4." (PMID 31915021, 2020). "Immunohistochemically, the tumor cells were focal positive for glial fibrillary acidic protein (GFAP) and negative for cytokeratin (CK) or S100." (PMID 32393192, 2020).
tumor (continued). "The distance from the tumor periphery to brain regions lacking detectable GFAP immunoreactivity was measured, showing increased tumor-induced astrogliosis in Cx43-null mice in comparison with wild-type mice." (PMID 32178454, 2020). "GFAP+ enteric glia promote tumorigenesis during early tumor development, but do so without inhibiting anti-tumor immunity or exacerbating intestinal inflammation." (PMID 33282743, 2020). "As observed in Ascl1WT tumors, GFAP did not cocolocalize extensively with GFP+ tumor cells, despite being expressed in some regions of the tumor." (PMID 32573857, 2020). "Histologically, residual neuroglia was positive for GFAP in PCNSL, suggesting that the tumor cells grew along the white matter fiber, which may be the main reason for the branch-like enhancement along the white matter fiber in PCNSL." (PMID 32561819, 2020). "Although tumor-associated macrophages represent up to 50% of the GBM cell mass, this staining did not exclude the possibility of another RPS27-positive, but GFAP- and CD68-negative cell type present within the tumor." (PMID 32349320, 2020). "The primary tumor from Patient 1 was negative for GFAP immunostaining, while those from Patient 2 and Patient 3 were positive for GFAP expression." (PMID 33353253, 2020). "The concordance of the results in these two distinct depletion systems gives us confidence that the observed reduction in tumor burden is a consequence of depletion of GFAP+ enteric glia and not a result of off-target effects." (PMID 33282743, 2020). "At PID9, high levels of GFAP mRNA were also detected in tissue surrounding the tumor, but not in tumor tissue." (PMID 32977526, 2020). "Additionally, RT-PCR also indicated the gene expression of iPSC-derived tumor tissue in three germ layers, demonstrating expressions of GATA4 in endoderm; HAND1 and GATA6 in mesoderm; and TUBB3, MAP2, and GFAP in ectoderm." (PMID 33224204, 2020). "HCCC, instead, is a tumor predominantly occurring in minor salivary glands, which is immunostochemically negative for S100, smooth muscle actin, calponin and glial fibrillary acidic protein (GFAP) but positive for pan-cytokeratins and p63." (PMID 32316524, 2020). "The morphology of this tumor resembles soft tissue myoepitheliomas, particularly those tumors with a myxoid pattern, but the neoplastic cells are negative for S100, GFAP and myogenic markers such as SMA, desmin." (PMID 31915021, 2020). "Through the analysis of the semi-serial sections, NG2/CSPG4 immunoreactivity was mutually exclusive from that of GFAP in tumor cells but not in reactive astrocytes." (PMID 32599896, 2020). "By immunohistochemistry, the tumor cells stained positively for S-100 (focal +), CD34 (strong +++) and Ki-67 (20%), and negatively for smooth muscle actin, pan-cytokeratin, neurofilament, pan-cytokeratin-L, GFAP, CD31, STAT6, ERG, myogenin, and MyoD1." (PMID 32590748, 2020). "Limited GFAP-positive immunoreactivity was noted at the margin of tumors and no GFAP-positive immunoreactivity was detected within the tumor in group A." (PMID 32456305, 2020). "IHC/immunofluorescence analysis of CD24+ and CD24- cell-initiating tumours identified diffuse CD24 expression throughout both tumour populations that did not co-label with GFAP or Olig2+." (PMID 30657775, 2019). "The results from day 14 after tumor implantation showed that many GFAP+ astrocytes activated in the nearby parenchyma of tumor border, and were independent of tumor types." (PMID 31106146, 2019). "Bcl-6, CD2, CD5, CD10, CD7, CD23, CD34, NF, TdT, multiple myeloma oncogene 1 (MUM-1) and glial fibrillary acidic protein (GFAP) were found to be negative in tumour cells." (PMID 31426757, 2019). "IHC performed on SCR shRNA xenografts showed the tumour cells to be negative for the expression of the IDH1R132H‐mutated protein product with strong nuclear ATRX expression and GFAP and EGFR immunopositivity." (PMID 30565681, 2019).
tumor (continued). "To examine if this same mechanism was operative in patient tissue and not an artefact of culture we assessed sequential (#1–4) GS tumour sections by IHC for αDG, EphA3, GFAP, pERK and Ki67." (PMID 31463571, 2019). "The tumor cells are diffusively positive for vimentin and S-100, focally positive for glial fibrillary acidic protein, and generally negative for epithelial membrane antigen, synaptophysin, chromogranin A, and neurofilament." (PMID 31689841, 2019). "Immunohistochemically, the tumor cells are positive for GFAP, CK7, ER, and PR, but negative for S-100, TTF-1, CAM5.2, and CK20." (PMID 31689791, 2019). "The tumor was negative for glial fibrillary acidic protein (GFAP) and isocitrate dehydrogenase (NADP(+)) 1 (IDH1) R132H." (PMID 31480400, 2019). "All specimens demonstrated strong positive immunostaining for S-100 and GFAP proteins, whereas the tumor cells were not immunoreactive to DOG1, c-Kit (CD117), CD34, SMA and desmin." (PMID 30045739, 2018). "Tumor cells demonstrated patchy positivity for GFAP with strong reticulin staining in GFAP negative areas." (PMID 29416795, 2018). "Likely, the GFAP/CD133+CD90+/CD44+ EPN cells infiltrated the normal brain parenchyma and have the best chance of escaping surgical resection and of becoming a source of tumor recurrence." (PMID 29774098, 2018). "Bcan-Ntrk1-induced tumors showed elevated percentage of Ki67-positive cells, were positive for OLIG2 and NESTIN, negative for the neuronal marker NeuN and GFAP-positive cells were almost exclusively detected at the normal/tumor border." (PMID 29654229, 2018). "Patients with longer time to tumor progression generally exhibited a decrease in circulating CD9+/SVN+ and CD9+/GFAP+/SVN+ exosomes immediately following survivin vaccination; whereas, those with early tumor progression had an increase in exosomes, despite anti-survivin immunotherapy." (PMID 29383115, 2017). "In 4 of the 5 tumor pairs (#3319, 9036, 1576, 2022), there were no major differences between primary and recurrent tumors, as nearly all cells were positive for GFAP and VIM." (PMID 29152094, 2017). "The population of P2RY12+ cells did not overlap with the population of GFAP positive tumor cells or reactive astrocytes." (PMID 28073370, 2017). "Confocal imaging 4 h after introduction of NPs into the brain confirmed that NPs were internalized by tumour cells, microglia/TAM and GFP/GFAP-positive tumour cells inside the tumour bulk, with significant uptake by activated microglia and reactive astrocytes at the tumour periphery." (PMID 28524852, 2017). "One patient (#7), who was the last of the patients with early progression to progress, experienced a detectable increase in CD9+/GFAP+/SVN+ exosomes 9 weeks following initial vaccination (row 4), which was 16 weeks prior to the detection of tumor progression on brain MRI scanning." (PMID 29383115, 2017). "The tumor included a heterogeneous population of GFAP and synaptophysin immunopositive cells and did not stain for either NeuN or IDH1 R132H." (PMID 29872694, 2017). "The tumor demonstrated extensive immunostaining with GFAP and OLIG2 (not shown), and was negative for BRAF V600E and for IDH1 R132H mutant protein." (PMID 29141672, 2017). "In the current study, increases in both CD9+/SVN+ and CD9+/GFAP+/SVN+ exosome levels, taken as a fraction of all CD9+ exosomes, proved to be associated with tumor progression; whereas, CD9+/GFAP+ exosomes did not." (PMID 29383115, 2017). "Unlike ENI, specimen tumor cells in this case were positive for GFAP and S100, but not synaptophysin and NeuN, which did not support the diagnosis of ENI." (PMID 28320419, 2017). "This latter patient (#1) without tumor progression experienced a 98% reduction in serum CD9+/GFAP+/SVN+ exosomes 9 weeks after initial vaccination and a 94% reduction at 22 months." (PMID 29383115, 2017). "Scattered GFAP-positive reactive astrocytes were found within and around the tumor tissue, but tumor cells were GFAP negative." (PMID 27806344, 2016).
tumor (continued). "A small proportion of transplanted neurosphere cells expressed glial fibrillary acidic protein (GFAP) or vimentin, markers of more differentiated cells, but this number increased significantly during tumor growth, indicating that these cells undergo differentiation in vivo." (PMID 26659251, 2016). "Endoxifen-induced tumours expressed GFAP, nestin, Sox2, Olig2, PDGFRa and doublecortin (Fig. 5E1-J1), and were indistinguishable from tumours generated by Adeno-Cre or Adeno-GFAP-Cre injection and as shown in Fig. 5E2-J3." (PMID 26704996, 2016). "The tumor cells stained positive for S-100, vimentin, CD56, and GFAP." (PMID 27247816, 2016). "On the other hand, the expression of CD166, CD133, CD44, A2B5, CD56, NGFR and DCX seemed to be higher in UA cells, but also not statistically significant, while the expression of CD9, Nestin, GFAP, CD24, PDGFRb, PDGFRa, MAP2, TUBIII, S100 were consistently high in both UA and tumor core samples and." (PMID 27605047, 2016). "In areas of white matter adjacent to tumour, occasional astrocytes were seen to stain with anti-S100P antibody; however, morphology and staining of serial sections with GFAP clarified that these were not tumour cells, thus avoiding any false positives." (PMID 27100728, 2016). "Immunohistochemical examinations showed that the tumor cells were synaptophysin- and NeuN-positive but GFAP-negative." (PMID 26376790, 2015). "Sox2/GFAP double-labeling revealed a consistent pattern of Sox2 immunopositivity both in reactive GFAP-immunopositive astrocytes and in GFAP-negative cells, at the interface of tumor and non-neoplastic brain." (PMID 25713758, 2015). "A minority population of cells stained co-positive for the astrocytic marker GFAP and endothelial marker CD105 or CD31 suggesting that these may be TDEC within the tumor mass." (PMID 26203665, 2015). "At day 7 post-injection most of the tumor cells were largely negative for GFAP in both groups with few cells showing positive staining." (PMID 26700636, 2015). "PDCD10 immunoreactivity was absent in proliferating tumor cells, endothelial cells and GFAP-positive cells, but exclusively present in the hypoxic pseudopalisading cells which underwent apoptosis." (PMID 26490252, 2015). "The tumor cells show strong immunoreactivity for synaptophysin, variable staining for NeuN, whereas GFAP stains are typically negative, which further confirmed that they were differentiating into neurons." (PMID 26376790, 2015). "Immunohistochemically, the tumor cells were positive for prolactin, chromogranin-A, and synaptophysin, but were negative for glial fibrillary acidic protein, S-100 protein, epithelial membrane antigen, and vimentin." (PMID 26228535, 2015). "The obtained tumor was negative for GFAP and showed high Nestin expression and weak expression of β3 Tubulin, and a high proliferation rate as indicated by positive Ki67 staining." (PMID 25275602, 2014). "In the present study, we also found a negative correlation between DcR3 and GFAP expression (r = −0.489, P < 0.01), which further indicated the close relationship between DcR3 level and the tumor differentiation." (PMID 24741354, 2014). "In the present case, immunohistochemistry revealed that the tumor was positive for GFAP, S-100 protein, vimentin, CD34, CD99 and D2-40 and negative for neuron markers (Syn and chromaffin protein/NeuN)." (PMID 24348765, 2014). "We also measured GFAP mRNA levels by quantitative RT PCR, but did not detect any increases suggesting increased glial differentiation of tumor cells (data not shown)." (PMID 24685274, 2014). "Several physiopathological mechanisms may explain increased GFAP levels in serum of GBM patients, including disruption of BBB and/or the extent of tumour angiogenesis or tumour necrosis." (PMID 26116110, 2014). "Tumor cells were negative for muscle-specific actin, epithelial membrane antigen, smooth muscle actin, cytokeratin pan, S100, desmin, glial fibrillary acidic protein, myogenin, MyoD1 and F8." (PMID 24758544, 2014).
tumor (continued). "DcR3 expression showed positive correlations with tumor pathological grade (r = 0.621, P < 0.01) and negative with GFAP expression (r = −0.489, P < 0.01)." (PMID 24741354, 2014). "The tumor cells are immunoreactive for S-100 proteins, calretinin, NSE, laminin and CD68 (Kp1), but they do not react with antibodies for neurofilaments or glial fibrillary acidic protein (GFAP)." (PMID 24349953, 2013). "The majority of GBM cells in non-irr tumor reflected their stem cell characteristics by a strong Nestin signal and a low GFAP presence." (PMID 24052948, 2013). "Correspondingly, GFAP-positive cells were located in the central tumor mass and not in the periphery (15.6% ± 1.8% center versus 1.2 ± 1.2, periphery;, where the tumor did progress." (PMID 24052948, 2013). "In U87, U251 and MRC-5 cells, the western blotting showed that the GFAP protein was expressed in the GFAP-positive U251 and U87 tumor cell lines as a major band of 49 kDa but not in the GFAP-negative MRC-5 cells, since MRC-5 was a normal cell line." (PMID 23420532, 2013). "We confirmed that the orthotopic C6 tumors used here consisted of densely packed tumor cells, were highly vascularized, did not express GFAP, and were surrounded by GFAP positive astrocytes, all consistent with previous reports." (PMID 23372821, 2013). "Immunohistochemical evaluation also showed the same expression pattern as the tumor from the surgery in 2007, with a positive immunoreaction for synaptophysin and a negative reaction for GFAP." (PMID 23840986, 2013). "The hNIS protein was detected as a major band corresponding to a molecular weight of 70 kDa in U251 and U87 tumor cell lines but was not expressed in the GFAP-negative MRC-5 cell line." (PMID 23420532, 2013). "On immunohistochemical staining, the tumor cells were positive for S-100 protein, but negative for glial fibrillary acidic protein (GFAP) and cytokeratin." (PMID 22989192, 2012). "In this orthotopic model, TAAs derived from tumor cells would not express the GFAP-GFP transgene; conversely, TAAs derived from non-tumor cells should express GFP." (PMID 22393407, 2012). "The tumor showed diffusely positive reactivity with cytokeratin (Pan), cytokeratin 19, cytokeratin 5/6, cytokeratin 7, EMA, vimentin, CD56, and NSE and also showed variable reactivity with glial fibrillary acidic protein (GFAP) and VEGF." (PMID 22472343, 2012). "To study TAAs, we used a GFAP-GFP transgenic mouse that expresses GFP under the control of the human GFAP promoter, which allows for isolation of astrocytes using fluorescence activated cell sorting (FACS) from normal and tumor brains." (PMID 22393407, 2012). "In this study, GFAP expression was evaluated using the following semi-quantitative scoring system: 0, no expression; 1, ≤20% of tumour cells expressing GFAP; 2, between 20% and 50% GFAP expressing cells; 3, ≥50% GFAP expressing cells." (PMID 21573151, 2011). "However, these GFAP−/NG2+/Olig2+ tumors showed hallmarks of oligodendrogliomas, a distinct tumor entity probably originating from the transformation of oligodendrocyte progenitors." (PMID 24212782, 2011). "An analysis of the immunohistochemical profile of the tumor cells showed positivity for vimentin, S-100 protein, and glial fibrillary acidic protein (GFAP), but not for smooth muscle actin (α-SMA) and cytokeratin 14 (CK14)." (PMID 22152025, 2011). "The surrounding sheets of tumor cells unrelated to vessels, show scattered GFAP, NFP and Syn positivity but no dendricity." (PMID 21080952, 2010). "Occasional neovascular channels remain quiescent with a single layer of GFAP negative tumor cells outside a thin silver positive BM." (PMID 21080952, 2010).